AQP4 (aquaporin 4)
Diseases named in the same sentence as AQP4 in open-access papers (continued):
Sharing a sentence is not in itself a finding about the gene and the disease.
Hypoglycemia (5 papers, 2014 to 2025). A decreased concentration of glucose in the blood. "In AQP4-deficient mice, hypoglycemia-induced secretion of pro-inflammatory factors, the degree of inflammatory response and the degree of BBB destruction were significantly lower than those in normal mice." (PMID 40406486, 2025). "Our finding of lower AQP4 expression in T1DM brains raises questions about whether reduced glymphatic activity is due to frequent hypoglycemia or decreased immune activity resulting from neuronal loss, as hypothesized for microglia alterations." (PMID 41023469, 2025). "However, AQP4 deletion preserved the loss of claudin-5 caused by hypoglycemia (#p < 0.05 vs. Hypo group)." (PMID 29793504, 2018). "To test whether AQP4 deficiency attenuated brain edema under acute hypoglycemic conditions, we quantified the extravasation of EB and brain water content in mice under severe hypoglycemia." (PMID 29793504, 2018). "It was previously shown that increased AQP4 and degradation of claudin-5 were involved in acute hypoglycemia-induced brain edema both in vivo and in vitro." (PMID 29793504, 2018). "AQP4 deletion attenuated BBB disruption after hypoglycemia, but injuries in the AQP4−/− + Hypo mice were still severe." (PMID 29793504, 2018). "In summary, our present study showed that AQP4 deficiency exerts a potent regulatory function on PPAR-γ expression in astrocytes, which, consequently, attenuates proinflammatory responses, hypoglycemia-induced BBB permeability, and brain edema." (PMID 29793504, 2018). "Here, in order to investigate the role of AQP4 deficiency in hypoglycemia-induced degradation of BBB components, we analyzed the expression of claudin-5, a major tight junction protein, and AQP4 via Western blot." (PMID 29793504, 2018). "We then studied the expression of AQP4 at the transcriptional and protein level at different time points after hypoglycemia." (PMID 25264602, 2014). "To determine whether the effect of AQP4 deletion on BBB disruption after hypoglycemia is involved in the immunomodulatory influence of AQP4 deletion, we examined TNF-α, IL-1β, and IL-6 mRNA expression in the brains of mice." (PMID 29793504, 2018). "Furthermore, immunofluorescence staining for AQP4 (green) and claudin-5 (red) was performed in the cortex of the brain after hypoglycemia in mice." (PMID 29793504, 2018). "Furthermore, we tried to identify possible new mechanisms of AQP4 deletion that are involved in the protection of BBB integrity by developing a model of hypoglycemia in AQP4 deletion mice." (PMID 29793504, 2018). "Thus, the knockdown of AQP4 significantly decreased hypoglycemia-induced high transendothelial permeability, indicating a protective role of AQP4 in a hypoglycemic in vitro BBB model." (PMID 29793504, 2018). "Based on these findings, we believe that the effect of AQP4 reduction may be protective in acute severe hypoglycemia." (PMID 29793504, 2018). "Therefore, in this study, we demonstrated the neuroprotective effect of AQP4 deletion in a mouse model of severe hypoglycemia." (PMID 29793504, 2018). "However, AQP4 deletion significantly reduced the increased water ratio in the hypoglycemia model by approximately 30% in the AQP4−/− + Hypo group." (PMID 29793504, 2018). "This analysis showed that AQP4 deletion decreased BBB permeability in the presence of hypoglycemia." (PMID 29793504, 2018). "However, the effect of AQP4 deletion regarding protection against hypoglycemia-induced blood-brain barrier (BBB) breakdown is unknown." (PMID 29793504, 2018). "Reduction in AQP4 may be protective in acute severe hypoglycemia." (PMID 29793504, 2018). "A positive correlation between Aqp-4 and GFAP protein levels are consistent with prior reports of increased Aqp-4 corresponding with increased gliosis in a model of hypoglycemia." (PMID 31708792, 2019).
Hypoglycemia (continued). "However, hypoglycemia induced significant increases in the extravasation of EB, and AQP4 deletion significantly decreased EB leakage (2.67 ± 0.28 vs. 3.51 ± 0.38 μg/g brain weight, p < 0.01), suggesting that AQP4 preserved the alteration of BBB permeability under acute hypoglycemic conditions." (PMID 29793504, 2018). "However, how AQP4 regulates the BBB and TJs in the context of acute severe hypoglycemia remains unclear." (PMID 29793504, 2018). "To date, the expression of AQP4 during hypoglycemia has not been studied." (PMID 25264602, 2014).
lung adenocarcinoma (5 papers, 2011 to 2023). A carcinoma that arises from the lung and is characterized by the presence of malignant glandular epithelial cells. "The present case is discussed with the lung adenocarcinoma specimen which was stained by aquaporin-4 (AQP4) and with literature review of NMOSD linked to immune checkpoint inhibitors." (PMID 36517738, 2022). "Higher transcript and protein levels of AQP4 in well-differentiated lung adenocarcinomas suggested an association with a more favourable prognosis." (PMID 21548930, 2011). "Therefore, we aimed to investigate how AQP3 and AQP4 protein expression in lung adenocarcinoma (ADC) biopsy samples correlate with clinical and pathological parameters." (PMID 36233821, 2022).
myopia (5 papers, 2008 to 2024). "In a chicken model of myopia, rapid axial elongation and movement of fluid into the vitreous cavity were associated with upregulation of aquaporin 4 in the nerve fiber layer." (PMID 39759766, 2024). "Both Kir4.1 and AQP4 have already been implicated in the development of myopia and their role as a conduit for movement of retinal fluid into the vitreous was suggested." (PMID 20019881, 2009). "As expected from our earlier studies that demonstrated upregulated AQP4 channel expression during form-deprivation myopia (FDM), the elevation of AQP4 at the vitreo-retinal border during minus lens-induced myopic development was also seen here." (PMID 20806048, 2010). "These considerations are consistent with the central role of Müller cells in myopia, because the endfeet of these cells express aquaporin 4 at interfaces with retinal capillaries, the vitreoretinal border and synapses in the plexiform layers to facilitate retinal signal transduction." (PMID 39759766, 2024). "Müller cells may also regulate the vitreous and retina fluid balance in myopia by expressing AQP4 in the end feet in chick FDM." (PMID 36418970, 2022). "The results demonstrate that the upregulation of AQP4 channel expression in the NFL is likely to be the conduit for water movement during the most rapid expansion of the vitreous chamber volume during early development of myopia." (PMID 20806048, 2010). "Retinal tissue was prepared either for western blot analysis to show the presence of the AQP4 protein in the chick retina or for immunolocalization using polyclonal AQP4 antibodies to determine regional distribution and intensity of labeling during the induction of form deprivation myopia (FDM)." (PMID 18334967, 2008). "Thus, on the basis of the hyperosmolarity seen across the retina and choroid of hatchling chickens made myopic by form deprivation (FD), we predicted an upregulation of retinal AQP4 expression during induction of myopia." (PMID 18334967, 2008). "The abnormal visual signaling in myopia may disturb osmotic homeostasis and alter aquaporin 4 expression in Müller cells, leading to excess fluid movement and deposition in the vitreous chamber and, potentially, reduced fluid outflow into the choroid, ultimately leading to ocular enlargement." (PMID 39759766, 2024).
neuritis (5 papers, 2022 to 2025). A neuropathy arising from inflammation of one or more nerves. "Anterior part of the optic nerve is preferentially injured in anti-MOG neuritis, whereas in AQP4-neuritis, it rather concerns the posterior part of the visual pathways." (PMID 34097296, 2022). "The overlapping neurological manifestations and negative AQP4-Ab-assay make it difficult to discover the primary cause of neuritis." (PMID 36349166, 2022).
neurological autoimmune diseases (5 papers, 2015 to 2026). "This requires the development of humanized mouse models that both bear an AQP4-expressing human tumor and are susceptible to developing the subsequent neurological autoimmune disease." (PMID 40963604, 2025). "The AQP4 null mice that generated a robust T cell reaction against the second extracellular loop of AQP4, loop C, did not develop autoimmune neurological disease as they do not express the target antigen." (PMID 25990016, 2015). "However, other autoantibodies, like AQP4 or DPPX which are established markers for neurological autoimmune diseases show also expression in non-neuronal tissues." (PMID 30038610, 2018).
retinal ischemia (5 papers, 2011 to 2021). A ischemic disease that involves the retina. "The importance of the glial water transport as pathogenic factor of retinal degeneration is indicated by the fact that aquaporin-4 gene disruption in mice protects against retinal cell death after retinal ischemia-reperfusion." (PMID 23755094, 2014). "Moreover, immunocytochemistry of glial fibrillary acidic protein (GFAP), glutamine synthetase (GS) and aquaporin-4 (AQP4) peptides on retinal sections were performed to study glial cell reactivity, glutamate metabolism and water accumulation, respectively after retinal ischemia." (PMID 22053184, 2011).
status epilepticus (5 papers, 2019 to 2023). Status epilepticus is defined as a continuous seizure lasting more than 30 min, or two or more seizures without full recovery of consciousness between any of them. "This was highlighted by the study of Kim and colleagues in which a reduction of AQP4 expression in brain tissue during the post-status epilepticus period was demonstrated, which in turn is associated with down-regulation of dystrophin and alpha-syntrophin complex." (PMID 37569297, 2023). "Status epilepticus (a prolonged seizure activity, SE) differently affects vasogenic edema formation and dystrophin-aquaporin 4 (AQP4) expressions between the rat hippocampus and the piriform cortex (PC)." (PMID 31795399, 2019). "Considering previous findings on disruption of the BBB during intense seizure activity, it has been hypothesized that AQP4 probably plays a crucial role in the elimination of excess water entering the brain due to disruption of the blood-brain barrier during an episode of status epilepticus." (PMID 37569297, 2023).
teratoma (5 papers, 2018 to 2024). A non-seminomatous germ cell tumor characterized by the presence of various tissues which correspond to the different germinal layers (endoderm, mesoderm, and ectoderm). "In all of these patients, teratomas revealed the expression of AQP4 and GFAP in areas containing neuroglial tissue." (PMID 35651803, 2022). "Teratoma was also diagnosed in 66% of patients with the coexistence of AQP4-IgG alone." (PMID 39449321, 2024). "However, in patients with AQP4-IgG+ NMOSD associated with OT, only 16.7% (1/6) of patients experienced relapse after removal of teratoma." (PMID 35651803, 2022). "Some patients may have coexisting antibodies such as anti-NMDAR or aquaporin-4 (AQP4) antibodies, which may indicate an underlying teratoma." (PMID 30364136, 2018). "GFAP antibody, AQP4 antibody, and NMDAR antibody are expressed in teratoma." (PMID 39464885, 2024). "Several studies have shown that early teratoma resection helps to reduce the recurrence of anti-NMDAR encephalitis, and interestingly, previously published cases suggest that this condition seems to also be applicable for AQP4-IgG+ NMOSD and MOG-EM." (PMID 35651803, 2022). "In addition, most of the patients with PNSs (including AQP4-IgG+ NMOSD, MOG-EM) had full recovery or almost full recovery after removal of teratoma and immunotherapy." (PMID 35651803, 2022).
thymoma (5 papers, 2014 to 2026). A neoplasm arising from the epithelial cells of the thymus. "We present a rare case of paraneoplastic neuromyelitis optica spectrum disorder (NMOSD) in a 50-year-old woman with a history of B3 thymoma, marked by dual positivity for AQP4-IgG and CV2/CRMP5 antibodies." (PMID 41878006, 2026). "This case underscores the association between thymoma and paraneoplastic NMOSD and suggests a potential interaction between AQP4- and CRMP5-related autoimmune responses." (PMID 41878006, 2026). "Herein, we report paraneoplastic neuromyelitis optica (NMO) associated with both anti-aquaporin-4 (AQP4) immunoglobulin G (IgG) and type 1 antineuronal nuclear antibody (ANNA-1) in an invasive thymoma patient." (PMID 25187234, 2014). "We have reported a case of paraneoplastic NMO associated with both AQP4-IgG and ANNA-1 autoantibodies in an invasive thymoma patient." (PMID 25187234, 2014). "However, there has been no report of paraneoplastic neuromyelitis optica (NMO) associated with both anti-aquaporin-4 (APQ4) immunoglobulin G (IgG) and type 1 antineuronal nuclear antibody (ANNA-1) in an invasive thymoma patient." (PMID 25187234, 2014). "In some cases, an immune response against AQP4 on thymoma cells may trigger NMOSD." (PMID 39872531, 2024). "Although rare, thymoma associated with visual symptoms has been reported in association with paraneoplastic autoantibodies, such as cancer-associated retinopathy (CAR) with anti-retinal antibodies, paraneoplastic optic neuropathy (PON) with anti-CRMP5 antibody, or NMO with AQP4-IgG." (PMID 25187234, 2014). "In NMOSD, some studies have shown that aquaporin 4 water channels (AQP4) are expressed at the neuromuscular junction in thymocytes of patients with MG and thymoma." (PMID 34439676, 2021). "In this regard, there is currently only one case report describing anti-Hu antibodies in a patient with anti-AQP4 positive NMOSD and recurrent thymoma." (PMID 28068933, 2017).
tuberculosis (5 papers, 2014 to 2025). A chronic, recurrent infection caused by the bacterium Mycobacterium tuberculosis. "Differential diagnoses included infective causes (viral, mycoplasma, Lyme disease, and tuberculosis {TB}) and inflammatory etiologies (NMOSD, including AQP4 and MOG antibody-related neuroinflammation)." (PMID 41393590, 2025). "It shows the usefulness of testing for anti-aquaporin-4 antibodies while evaluating neurological deterioration in patients with tuberculosis." (PMID 25169022, 2014). "This is the first reported case of anti-aquaporin-4 antibody-positive NMO spectrum disorder in a patient with active tuberculosis." (PMID 25169022, 2014). "Moreover, associated undiagnosed tuberculosis at the time of presentation and negative AQP4-Ab clouded the diagnosis and delayed the treatment." (PMID 36349166, 2022).
type 1 diabetes (5 papers, 2012 to 2023). "For example, some of the most significantly altered MAM proteins in our Type 1 diabetes model included LGALS3, GPX4, PDGFR, AQP4, and alphaA- and alphaB-crystallin (CRYAA and CRYAB)." (PMID 36139394, 2022).
uveitis (5 papers, 2007 to 2025). An inflammatory process affecting a part of or the entire uvea. "These latter data are consistent with the slightly reduced expression of AQP4 observed during endotoxin-induced uveitis." (PMID 20383338, 2010). "In this study, we investigated the expression of Kir4.1 and AQP4 in the retina during endotoxin-induced uveitis (EIU) in rats." (PMID 17356517, 2007). "Interestingly, during endotoxin-induced uveitis, Kir4.1 and AQP4 expression were differentially regulated on Müller cells and the swelling characteristics of these cells were altered by inflammation." (PMID 20383338, 2010).
asthma (4 papers, 2014 to 2023). "Among the various lung injuries investigated, there was a reduction in AQP1 expression or activity, and AQP1 and AQP4 mRNA expression was downregulated in allergen-induced mouse models of asthma." (PMID 25009607, 2014). "Another study on ovalbumin-induced asthma models also reported reduced mRNA levels for AQP1, AQP4, and AQP5 but elevated AQP3 mRNA levels." (PMID 30397774, 2019). "Asthma models based on ovalbumin instillation exhibit changes in expression levels of AQP1, AQP3, AQP4, and AQP5." (PMID 30397774, 2019). "The role of AQP4 in asthma is not clear, but since the progression of asthma usually includes edema, a contribution to fluid clearance cannot be ruled out." (PMID 29977890, 2018).
Ataxia (4 papers, 2018 to 2024). Ataxia refers to impaired coordination of voluntary muscle movement. "Neuromyelitis optica spectrum disorders (NMOSD) with AQP-4 antibodies as well as MOG-antibody associated diseases (MOGAD) may present with ataxia." (PMID 39735552, 2024). "In more than half of our patients with NMDARE-associated ataxia, we were able to exclude the presence of MOG, AQP-4, KLHL11, and GluK2 antibodies, all of which have previously been associated with both NMDAR-E and CNS neurological deficits including ataxia." (PMID 39735552, 2024). "As MOG, AQP-4, KLHL11, and GluK2 antibodies have been identified in NMDAR-E patients and have been associated with neurological symptoms including ataxia, we tested available sera for all four antibodies." (PMID 39735552, 2024). "Another point that should be mentioned is occurrence of vertigo and ataxia in two of patients as first presentations of NMOSD, which shows probable brain lesions in regions with high expression of aquaporin 4 channels." (PMID 30210729, 2018). "Cerebellar ataxia with and without additional neurological symptoms is commonly neither explained by concomitant AQP-4 antibody-positive NMOSD or MOGAD nor KLHL11 or GluK2 antibodies." (PMID 39735552, 2024). "In all five patients with cerebellar ataxia tested, MOG, AQP-4, GluK2, and KLHL11 antibodies were negative." (PMID 39735552, 2024). "Serum was tested negative for MOG, AQP-4, KLHL11, and GluK2 antibodies in five of eight patients with cerebellar ataxia (Cases 3–5, 7, and 8)." (PMID 39735552, 2024).